SPATA41 (spermatogenesis associated 41)
Synonyms: FLJ42289; HSD47
Gene: Long non-coding RNA gene on chromosome 15 (100,344,047 to 100,373,838, reverse strand). Ensembl gene ENSG00000189419.
Diseases named in the same sentence as SPATA41 in open-access papers:
SPATA41 is named in the same sentence as 2 diseases in open-access papers, as found by Europe PMC text mining. Sharing a sentence is not in itself a finding about the gene and the disease. The quoted sentences say what the papers report.
cancer (1 paper, 2022). A tumor composed of atypical neoplastic, often pleomorphic cells that invade other tissues. "Moreover, increased expression of LC3 II/LC3 I and decreased expression of p62 indicated that autophagy may also be involved in the regulative process of SPATA41 in cancer cells." (PMID 36105081, 2022).
tumor (1 paper, 2022). "Consistent with our previous result, SPATA41 expression increased significantly in tumor and adjacent tumor tissue in comparison with normal lung tissue." (PMID 36105081, 2022).